PPA2 (inorganic pyrophosphatase 2)
Diseases named in the same sentence as PPA2 in open-access papers (continued):
Sharing a sentence is not in itself a finding about the gene and the disease.
infection (3 papers, 2020 to 2023). The state of being infected such as from the introduction of a foreign agent such as serum, vaccine, antigenic substance or organism. "We previously reported that impairment of the mitochondrial PPA1 homologue PPA2 underlies an IMD presenting with (infection-triggered) early infantile or adolescent sudden cardiac death (the latter of which is presumably induced by moderate alcohol consumption)." (PMID 37999237, 2023). "Infection induces the cellular response of hyperthermia, which in the case of PPA2-deficient individuals may mean a further reduction in residual PPA2 enzyme function." (PMID 34400813, 2021). "The role of external tissue or cellular stressors such as alcohol or infection may impact the disease course of individuals carrying pathogenic PPA2 variants." (PMID 34400813, 2021). "PPA2 could induce immune responses against bacterial pathogen infection through a mechanism that may be related to the JA pathway." (PMID 32295118, 2020). "This might explain why PPA2 could help plants resist bacteria rather than fungi pathogen infection." (PMID 32295118, 2020).
mitochondrial disease (3 papers, 2016 to 2021). "The role of pyrophosphatase 2 (PPA2) in mitochondrial disease has recently emerged with the discovery of biallelic PPA2 variants that cause a partial loss of gene function (hypomorphs) within families affected by recurrent sudden cardiac death in siblings." (PMID 34400813, 2021). "Because PPA2 functions within the mitochondrial matrix, variants in this nuclear‐encoded protein cause mitochondrial diseases." (PMID 31705601, 2020). "We have used whole-exome sequencing in ten individuals from four unrelated pedigrees to identify biallelic missense mutations in the nuclear-encoded mitochondrial inorganic pyrophosphatase (PPA2) that are associated with mitochondrial disease." (PMID 27523597, 2016). "These individuals show a range of severity, indicating that PPA2 mutations may cause a spectrum of mitochondrial disease phenotypes." (PMID 27523597, 2016). "We have identified hypomorphic missense mutations in the human gene of the mitochondrial inorganic pyrophosphatase encoded by PPA2 (MIM: 609988) in a multicenter study by exploring undiagnosed cases with presumed mitochondrial disease using whole-exome sequencing (WES)." (PMID 27523597, 2016). "Individual II-1 from family 10 was diagnosed prenatally with PPA2-related mitochondrial disease." (PMID 34400813, 2021). "However, a small study of 13 patients with mitochondrial depletion syndromes found no pathogenic mutations identified in the PPA2 of these patients and therefore, investigators did not believe PPA2 mutations are a common cause of mitochondrial diseases in humans." (PMID 31705601, 2020).
bacterial infection (1 paper, 2020). "PPA2 pretreatment significantly increased plant resistance against bacterial infection in both Arabidopsis and rice, in conjunction with increases in the level of jasmonoyl-isoleucine and 12-oxo-phytodienoic acid." (PMID 32295118, 2020). "Together, these results indicated that PPA2 effectively protected plant cells against bacterial infection through regulating ROS production." (PMID 32295118, 2020). "Nonetheless, we found that PPA2 can induce immune responses against bacterial infection in both Arabidopsis and rice, the mechanism of which might be related to the reactive oxygen species (ROS) and JA pathway." (PMID 32295118, 2020). "Our results thus indicate that PPA2 enhances plant defenses against bacterial infection through the jasmonic acid pathway, and that as a water-soluble compound that can promote the synthesis of primary metabolites it has broad potential applications in agriculture." (PMID 32295118, 2020). "Pretreated PPA2 in plants could induce resistance responses against pathogen attacks, especially bacterial infection." (PMID 32295118, 2020).
neurological disease (1 paper, 2021). "Functional analysis of these genes showed that UQCRH participates in cardiac muscle contraction, PPA2 is closely related to sudden cardiac failure (SCD), and OGT, as the interacting gene partner of PANO1, is associated with neurological disease." (PMID 34290742, 2021).
PPA2 also shares sentences with these, for which no sentence is quoted: cardiac arrhythmia (2 papers); sudden cardiac arrest (2); viral myocarditis (2); autoimmune disease (1); breast invasive carcinoma (1); cardiac arrest (1); cardiac disease (1); colorectal adenoma (1); death (1); epilepsy (1); infectious disease (1); lactic acidosis (1); Myocardial fibrosis (1); myocarditis (1); peripheral neuropathy (1); pneumonia (1); ptosis (1); rectum adenocarcinoma (1); sarcoma (1); uveal melanoma (1); ventricular dilatation (1).